SYP (synaptophysin)
Diseases named in the same sentence as SYP in open-access papers (continued):
Sharing a sentence is not in itself a finding about the gene and the disease.
infection (17 papers, 2013 to 2024). The state of being infected such as from the introduction of a foreign agent such as serum, vaccine, antigenic substance or organism. "Thirteen weeks post-infection, loss of synaptophysin staining was found in the radiate layer." (PMID 34208561, 2021). "Our results demonstrated a notable decrease in the levels of synaptotagmin-1 and synaptophysin post-infection." (PMID 39640294, 2024). "Instead, the productive infection of the microglia activated them and impaired synaptophysin expression, dendritic density, and axonal structure in the neurons." (PMID 38793575, 2024). "Infection of mice with AAV-Tat for 21 days didn’t change the expression levels of β3-Tubulin or PSD95 but significantly reduced synaptophysin expression level, indicating that neurotoxicity of HIV-1 Tat protein is attributed to its penetrating property." (PMID 32814783, 2020). "High content screening analysis with immunofluorescence staining for synaptophysin revealed a 26% and 19% decrease in synapse density on neurons at 24 h and 48 h of infection, respectively." (PMID 32390638, 2020). "We found that synaptic proteins including synaptotagmin and synaptophysin were markedly decreased after AAV2-hTau infection." (PMID 30542264, 2018). "In addition, synaptophysin staining was also progressively reduced in the proximal dendrite region of CA1 pyramidal cells until the nineteenth week after infection." (PMID 34208561, 2021). "Our results showed that infection of mice for 21 days with AAV-Exo-Tat didn’t change the expression levels of β3-Tubulin, PSD95 or synaptophysin." (PMID 32814783, 2020). "To determine the cortical layer(s) in which IL→PreL (or PreL→IL) terminate within the respective other cortical area, we applied combinatorial infection of CAV2-Cre and AAV9-flex-synaptophysin-Myc to infect these neurons, visualizing their synaptic terminals." (PMID 30006525, 2018). "Ad-RFP-Neurog3 infection induced expression of the pan-endocrine markers chromogranin A (CHGA) and synaptophysin in both primary CD133+ duct cells and cultured spheres (and data not shown)." (PMID 24252877, 2013). "The expression levels of PSD95 and synaptophysin decreased significantly after infection, while NeuN expression was not affected by the infection." (PMID 35414007, 2022). "The expression levels of PSD95 and synaptophysin decreased significantly after infection, while NeuN expression was not affected by A. cantonenesis infection." (PMID 35414007, 2022). "We found that, similar to wild-type neurons, FL1-treated FL neurons display defined clusters of PSD95 and Synaptophysin, compared to Flailer neurons, where the expression of PSD95 is distributed broadly throughout the dendritic shafts and opposing to Synaptophysin signal after 10 days of infection." (PMID 37957716, 2023).
neurological disorders (9 papers, 2012 to 2023). "Therefore, it is probable that abnormal expression of PSD95 and SYP may change synaptic plastic events that contribute to the synapse abnormalities associated with neurological disorders." (PMID 35318322, 2022). "The findings suggest that synaptophysin levels can serve as a marker of synaptic density to assess synaptic plasticity in various neurological disorders." (PMID 37605213, 2023). "Synaptophysin is the major synaptic protein necessary for neurotransmission, which is a well-known marker for neurodegeneration in various neurological diseases." (PMID 29064407, 2017). "TNF produced by activated glial cells in inflammatory or degenerative neurological diseases affects neurites by acting on the kinesin-tubulin complex and inhibiting axonal mitochondria and synaptophysin transport via JNK in hippocampal cultures." (PMID 23776493, 2013).
epithelial neoplasm (5 papers, 2015 to 2022). A benign or malignant neoplasm that arises from and is composed of epithelial cells. "The tumor phenotypes were strongly positive for CAM 5.2, which is a cytokeratin (CK) marker, and synaptophysin (Syp), which is a neuroendocrine marker, indicating that the tumor was an epithelial neoplasm with neuroendocrine differentiation." (PMID 36528621, 2022).
neurodevelopmental disorder (5 papers, 2016 to 2024). A behavioral and cognitive disorder with onset during the developmental period that involves impaired or aberrant development of intellectual, motor, or social functions. "SYP mutations that affect VAMP2 trafficking are associated with neurodevelopmental disorders, and understanding the molecular sequence of events underlying SYP/VAMP2-mediated trafficking is vital for addressing public health concerns." (PMID 34616284, 2021). "Mutations in proteins that regulate endocytosis, such as synaptophysin and dynamin 1, have also been linked to neurodevelopmental disorders involving movement abnormalities and EEG disturbance." (PMID 30107533, 2018). "Included in the endocytosis genes linked to neurodevelopmental disorders is SYP, which encodes the abundant SV protein synaptophysin." (PMID 28887151, 2017). "We report here a novel SYP mutation identified in a patient with a severe neurodevelopmental disorder." (PMID 28887151, 2017). "In addition to neurodevelopmental disorders, synaptophysin dysfunction is also linked to neurodegenerative conditions such as Alzheimer’s disease (AD)." (PMID 26903854, 2016). "Therefore the perturbation or loss of synaptophysin function has been linked to series of neurodevelopmental disorders that are associated with deficits in higher brain function." (PMID 26903854, 2016). "Thus altered sybII retrieval due to synaptophysin dysfunction may be a potentially common mechanism underlying specific neurodevelopmental disorders." (PMID 28887151, 2017).
CNS tumors (4 papers, 2018 to 2025). "Common immunostains that can be used in approaching CNS tumors with an oligodendrocyte-like pattern include IDH, neuronal markers (synaptophysin, neurofilament protein, and NeuN), EMA, and GFAP." (PMID 35885538, 2022). "The recently described entity “CNS tumor with PLAGL amplification” (particularly PLAGL2 in infants and toddlers) also shows overlapping embryonal features with the tumors in this series, nonetheless with a different immune-profile—OLIG2 being mostly negative, and synaptophysin being patchy and weak." (PMID 38500181, 2024).
metabolic disorder (2 papers, 2020 to 2023). "The D-serine supplement also reversed metabolic disorders in ScKO mice and hippocampus PSD95 and Synaptophysin expression levels in ScKO mice and old mice." (PMID 36928253, 2023).
central nervous system diseases (1 paper, 2022). "Synaptic proteins, including synaptophysin, PSD-95 and drebrin, perform an essential role in the pathogenesis of central nervous system diseases." (PMID 35631310, 2022).
gastrointestinal tumors (1 paper, 2023). "Recently, INSM1 has emerged as an additional general neuroendocrine marker because it was shown to have better diagnostic ability than synaptophysin and chromogranin A in gastrointestinal tumors." (PMID 37027114, 2023).
Head and Neck Tumors (1 paper, 2025). "In the previous World Health Organization (WHO) classification of Head and Neck Tumors (4th edition), synaptophysin (SYP), chromogranin A (CgA), and CD56 have been recommended as immunohistochemical markers of neuroendocrine differentiation." (PMID 39937015, 2025).
inflammation (1 paper, 2022). Aberrant reaction of the microcirculation characterized by movement of fluid and leukocytes from the blood into extravascular tissues. "The present study suggested that CS exposure caused lung inflammation, hippocampal neuroinflammation, suppression of synaptophysin expression, and spatial and working memory deficits." (PMID 35351173, 2022).
SYP also shares sentences with these, for which no sentence is quoted: angiosarcoma (4 papers); breast (4); leiomyoma (4); ependymoma (3); metastatic disease (3); teratoma (3); anaplastic astrocytoma (2); brain disease (2); carcinoid tumour (2); cervical cancer (2); cognitive disorder (2); desmoplastic small round cell tumor (2); granulosa cell tumor (2); inflammatory myofibroblastic tumor (2); insomnia (2); leukemia (2); mucinous adenocarcinoma (2); smooth muscle tumor (2); thymic carcinoma (2); undifferentiated carcinoma (2); adenoid cystic carcinoma (1); adenosquamous carcinoma (1); adrenal carcinoma (1); allergic rhinitis (1); alveolar rhabdomyosarcoma (1); angiomyolipoma (1); anxiety disorder (1); astrocytic tumor (1); Atrophy (1); autism spectrum disorder (1).
A further 108 diseases each share a sentence with SYP in 1 paper.